TNF (tumor necrosis factor)
Diseases named in the same sentence as TNF in open-access papers (continued):
Sharing a sentence is not in itself a finding about the gene and the disease.
atopic dermatitis (200 papers, 2008 to 2026). "Chronic inflammation is characteristic of atopic dermatitis, primarily caused by increased levels of pro- inflammatory cytokines such as IL-6 or TNF-alpha." (PMID 38892934, 2024). "Published data show that the over expression of Th2 cytokines is prevalent in the acute phase of lesions caused by atopic dermatitis, while in the meantime, other proinflammatory cytokines, such as IL-6 and TNF-α, are over expressed in the chronic phase." (PMID 35883395, 2022). "Like TNF, reductions in sTNFR2 significantly associated with improvement in AD as measured by SCORing Atopic Dermatitis (SCORAD) metric (a metric which combines clinical scores for itch, rash, and sleep disturbance)." (PMID 36605199, 2022). "It is well known that the activation of the degradation of IκB-α, STAT-1, and MAPK in keratinocytes are associated with AD, and keratinocytes stimulated with TNF-α/IFN-γ are widely used for verification of the in vitro efficacy of anti-atopic dermatitis." (PMID 34500860, 2021). "Recently, resveratrol was shown to effectively reduce the expression of HMGB1, RAGE, and various cytokines, including TNF-α and IL-4, in inflamed skin caused by atopic dermatitis." (PMID 26950148, 2016). "IL-4 and TNF-α are risk factors for developing atopic dermatitis." (PMID 35646146, 2022). "Similarly, a study on the therapeutic mechanism of BV in atopic dermatitis lesions caused by ovalbumin (a major egg white protein) found that BV inhibited pro-inflammatory cytokines, such as TNF-α." (PMID 36287932, 2022). "Therefore, this study aimed to investigate the effect of SFII on TNF-α/IFN-γ-induced atopic dermatitis (AD)-associated cytokines, such as thymus- and activation-regulated chemokine (TARC) and macrophage-derived chemokine (MDC)." (PMID 34208434, 2021). "Topical treatment regimen consisting of PPARα activator showed potent anti-inflammatory effects in murine models of atopic dermatitis and in irritant and allergic contact dermatitis, which were associated with reduction in pro-inflammatory cytokines TNF-α and IL-1α." (PMID 27611371, 2016). "It is postulated that the attenuation of the Th1 immune pathway with TNF-α inhibition causes a shift towards a type 2 helper T-cell (Th2) immune response, leading to the development of skin lesions grossly and histologically consistent with the Th2 mediated disease atopic dermatitis." (PMID 34159000, 2021). "The atopic dermatitis cell model was established by co-stimulating with TNF-α (10 ng/mL) and IL-4 for 48 h." (PMID 41556698, 2026). "Some of the overlapping targets between propolis and UV allergic dermatitis were enriched in the TNF signaling pathway, C-type lectin receptor signaling pathway, and parathyroid hormone synthesis, secretion, and action pathways." (PMID 40232010, 2025). "TNF-α, singly or in combination with Th2 cytokines, modulates the states of lipids in the epidermal barrier in AD lesional skin, which supports the inflammatory contribution of TNF-α during the development of atopic dermatitis." (PMID 40565595, 2025). "In the complex pathophysiology of atopic dermatitis, TNF-α emerges as a pivotal pro-inflammatory cytokine that compromises skin barrier integrity while potentiating Th2-type immunity." (PMID 41471858, 2025). "In cells treated with BPF, gene sets enriched included GPCRs Family activating Expression Targets in Bone, TNF activating NF-kB Expression Targets, and Acute Phase in Atopic Dermatitis, among others." (PMID 41012393, 2025). "This study is the first to use a TNF-α/IFN-γ-induced human keratinocyte cell line to model the inflammatory response of atopic dermatitis and to elaborate on the mechanism of action of brianolide in detail." (PMID 40563511, 2025). "This study first utilized TNF-α/IFN-γ-induced human keratinocyte cell lines (HaCaT) to simulate the inflammatory response of atopic dermatitis." (PMID 40563511, 2025).
atopic dermatitis (continued). "There were 28 core targets related to UVB-induced allergic dermatitis, of which hub proteins were TNF-α, NFKB1, MMP-9, and IL-2." (PMID 40232010, 2025). "The consistent inhibition of TNF-α production by BBR across S. aureus strains identified from multiple individuals with atopic eczema highlights its potential as a therapeutic option for S. aureus-exacerbated atopic eczema." (PMID 39404402, 2024). "Inhibition of TNF-α-induced E-selectin expression is crucial in alleviating the symptoms of inflammatory skin diseases, particularly atopic dermatitis." (PMID 39683963, 2024). "The most frequent reasons for teleconsultation were paradoxical psoriasiform lesions (n = 13, 33.3%) due to anti-TNF agents, hidradenitis suppurativa (n = 4, 10.3%), and atopic dermatitis (n = 4, 10.3%)." (PMID 38469167, 2024). "Atopic dermatitis is characterized by the excessive production of inflammatory cytokines, such as tumor necrosis factor-alpha (TNF-α) and IL-6, which are closely related to inflammation and pruritus." (PMID 39519379, 2024). "Among the isolated compounds, compounds 2–5, 7, 9, and 10 showed inhibitory effects on inflammatory cytokines (IL-1β, IL-6, and TNF-α) related to atopic dermatitis against TNF-α/IFN-γ-stimulated HaCaT keratinocytes at 10 μM." (PMID 39519643, 2024). "Research on atopic dermatitis has shown the significant role of cytokines, including TNF-α, IL-4, IL-13, and IL-31, in the pathogenesis and symptoms of this condition." (PMID 39683963, 2024). "SF-7343 (King George Island, Antarctica), and it inhibited the secretion of IL-8 and IL-6 in tumor necrosis factor-α/interferon-γ-treated HaCaT cells in an inflammatory disease, atopic dermatitis." (PMID 39452841, 2024). "The graph of Network Pharmacology Survey shows that the effect of silica and silver nanoparticles on the expression of various genes such as IL4, IL6, IL8 and TNFα leads to the occurrence of various skin diseases such as atopic dermatitis." (PMID 38454025, 2024). "Another preparation of ISA-containing extract from I. helenium can attenuate the atopic dermatitis-like symptoms caused by dinitrochlorobenzene in mice, besides its decrease in the expression of IL-1, IL-4 and TNF-α in TNF-α-stimulated HaCaT cells." (PMID 39376605, 2024). "The serum levels of TNF-α and IL-4 were measured in atopic dermatitis mice using ELISA kits, which were observed to be significantly decreased after topical application of FCS." (PMID 38255849, 2024). "Keywords with high intermediary centrality were “atopic dermatitis”, “cardiovascular disease”, “clinical feature”, and “TNF-alpha”, suggesting possible turning points in research." (PMID 36837593, 2023). "Modulation of immune system by inhibition of IgE serum levels and cutaneous edema.Reduction of IL-4, IFN-γ, and TNF-α production.Decrease of lymph node size in atopic dermatitis mouse." (PMID 37685100, 2023). "According to previous studies, epithelial cells and keratinocytes damaged by atopic dermatitis produce proinflammatory cytokines (such as TNF-α, IL-1β, IL-6, and IL-8) and chemokines (such as CCL17/TARC, CCL22/MDC)." (PMID 36793948, 2023). "In DNCB-induced atopy mouse model, illumination with visible red (650 nm) alleviates symptoms of atopic dermatitis and restores cytokine levels such as IL-6 and TNF-α to normal." (PMID 36979014, 2023). "High immunoexpression of INF-γ was noted by immunohistochemistry (IHC) in inflamed regions of tissues of 12 vulvar LS while increased levels of INF-γ, IL-4, TNF-α and IL-10 were observed in atopic dermatitis." (PMID 35103930, 2022). "TNF-α is a systemic inflammatory cytokine and has the ability to kill tumor cells in atopic dermatitis in vitro." (PMID 35457288, 2022). "Inflammatory stimuli such as TNF-α/IFN-γ are used in many skin disease studies because they can mimic the symptoms of atopic dermatitis such as skin inflammation in HaCaT cells." (PMID 36158872, 2022).
atopic dermatitis (continued). "In atopic dermatitis, damaged epithelial cells and keratinocytes produce proinflammatory cytokines and chemokines such as TNF-α, IL-1β, IL-6, IL-8, CCL17, and CCL22." (PMID 36158872, 2022). "Angelicae Gigantis Radix attenuated scratching behavior, and 2,4-dinitrochlorobenzene-induced atopic dermatitis-like skin lesions by reducing serum IgE, histamine, TNF-α, IL-6, and COX-2 expression in skin tissue from mouse models." (PMID 35215322, 2022). "According to the results of the in vitro study, cytokines and activators related to the pathogenicity of atopic dermatitis, such as TNF-α and IFN-γ, can induce inflammation and allergic reactions." (PMID 34361003, 2021). "Stimulation of HaCaT cells by TNF-α/IFN-γ is widely used to find potential candidates for the treatment of atopic dermatitis." (PMID 34361003, 2021). "TGF-β secreted by human umbilical cord mesenchymal stem cells can inhibit TNF-α and relieve atopic dermatitis." (PMID 35069596, 2021). "Although TNF-α inhibitors are usually well-tolerated, various cutaneous side effects are frequently observed, including eczematous or atopic dermatitis-like eruptions." (PMID 34159000, 2021). "Enterobacteriaceae (a genus of Proteobacteria phylum) was negatively related to TLR4-induced TNF-α, and α-diversity of Bacteroidetes and Actinobacteria were lower in atopic eczema infants versus the controls." (PMID 34335634, 2021). "Mast cell-mediated inflammatory cytokines (e.g., TNF, IL-1, IL-4, and IL-6) occur as part of the tissue remodeling related to atopic dermatitis and allergic asthma, and in many other scenarios characterized by chronic allergic inflammation." (PMID 32932637, 2020). "It was reported that 60% ethanol/water extraction of P. densiflora bark regulated wound healing-involved cytokines such as interleukin (IL)-4, IL-5, and tumor necrosis factor alpha, resulting in attenuated atopic dermatitis." (PMID 32325920, 2020). "In a study of atopic dermatitis, AD-MSCs exosomes significantly reduced mRNA expression of various inflammatory cytokines such as interleukin (IL)-4, IL-23, IL-31, and tumor necrosis factor-α (TNF-α) in atopic dermatitis skin lesions of the mouse model." (PMID 32483483, 2020). "Second, for the treatment of atopic dermatitis, C. asiatica significantly reduced the inflammation response (TNF-α ↓, IL-1β ↓, IL-8 ↓, IL-4 ↓, and IL-13 ↓), and also the local immune response (IgE ↓)." (PMID 33013406, 2020). "At the onset of atopic dermatitis, skin inflammation occurs and the expression levels of inflammatory markers, such as TNF-α, IL-6, iNOS, and COX-2, increase." (PMID 32545274, 2020). "OIR3 was able to reduce oxazolone-induced skin inflammation in allergic dermatitis mouse model via the inhibition of TNF-α, IL-1β and IL-6 mRNA expression." (PMID 31775224, 2019). "Previous studies also found that this plant suppressed TNF-α level of atopic dermatitis of human keratinocyte cells and LPS-mediated RAW 264.7 macrophage cells." (PMID 31829185, 2019). "In the present study, we evaluated the therapeutic effects of SF in a mouse model of Dermatophagoides farinae body-induced atopic dermatitis (AD) and in tumor necrosis factor-α and interferon-γ-stimulated HaCaT keratinocytes." (PMID 31007602, 2019). "Research has also shown that U. rhynchophylla relieves atopic dermatitis and the indole alkaloids of U. rhynchophylla have anti-inflammatory mediators such as IL-1β, NO, and TNF-α." (PMID 31116257, 2019). "Atopic dermatitis increased the expression levels of IL-4, IL-13, IL-6, IL-17, IFNγ, and TNFα but decreased the expression of IL-10 in BALB/c mouse, in an SOCS1-dependent manner." (PMID 30459600, 2018). "It has been shown that resveratrol provides protection against ADR via inhibition of the AKT/NF-κB signaling pathway as well as through suppression of high morbidity group box 1 (HMBG1), RAGE, TNF-α, and IL-4 in skin inflammation induced by atopic dermatitis." (PMID 29937497, 2018).
atopic dermatitis (continued). "GGWE also attenuated atopic dermatitis induced by dust mite extract via the reduction of inflammatory mediators such as NO and TNF-α." (PMID 30274192, 2018). "NFκB-p65 and STAT-1 are transcription factors that are critically involved in atopic dermatitis-related signaling in TNF-α/IFN-γ–stimulated HaCaT cells." (PMID 29932162, 2018). "In previous reports, atopic dermatitis-like spongy changes and reduction of ceramide production induced by cytokines such as IL-1α and TNFα in epidermal cells were observed." (PMID 29132429, 2017). "In the sensitization and elicitation phase of allergic dermatitis, IL-1β and TNF-α play a pivotal role." (PMID 29029618, 2017). "Inflammatory mediators such as the Th2 cell–derived cytokines IL-4 and IL-31 and TNF-α have been shown to impair epidermal differentiation and have been suggested to play important roles in the pathogenesis of atopic dermatitis." (PMID 23157658, 2013). "We showed that elevated expression of AQP3 led to a reduced expression of differentiation markers, filaggrin in particular and an increased expression of CCL5 and TNFα, two of the most prominent cytokines in atopic dermatitis." (PMID 24260356, 2013). "Atopic dermatitis is a T-cell-mediated disease and characterized with strong inflammatory cytokines production such as tumor necrosis factor-α (TNF-α)." (PMID 23533483, 2013). "Importantly, in an atopic dermatitis-like cell model induced by TNFα/IFNγ, LF216EV significantly modulated the expression of immune regulatory genes (TSLP, TNFα, IL-6, IL-1β, and MDC), indicating its potential functionality in atopic dermatitis." (PMID 40028723, 2025). "In atopic dermatitis-like skin lesions, laminarin alleviates inflammation and modulates immune responses by suppressing IgE hyperproduction, mast cell infiltration, and the release of pro-inflammatory cytokines such as IL-1β, TNF-α, MCP-1, and MIP-1α." (PMID 41303564, 2025). "For instance, syringic acid alleviates C. acnes-induced inflammation by activating Nrf2 and suppressing ROS accumulation, while gentiopicroside reduces ROS levels in TNF-α/IFN-γ-stimulated keratinocytes by regulating the Keap1–Nrf2 axis in an atopic dermatitis model." (PMID 40573738, 2025). "Sleep disturbances in atopic dermatitis are not only due to sleep deprivation related to nighttime itching but also to dysregulation in the release of inflammatory mediators (IL-1b, IL-2, TNF-a, IFN-g, IL-6, IL-4, and IL-10) and neuroendocrine molecules such as cortisol and melatonin." (PMID 38731996, 2024). "Also, in an experimental study, Roc decreased significantly IL-8 and TNF-α cytokines production in the dorsal skin of mice subjected to atopic dermatitis." (PMID 38402151, 2024). "Therefore, the present study investigated the effects of A. koraiensis leaf extract and its compounds on TNF-α/IFN-γ-induced HaCaT keratinocytes to identify potential therapeutic agents for atopic dermatitis." (PMID 39519643, 2024). "Thus, keratinocytes from patients with atopic dermatitis present elevated mitosis and continuous production of pro-inflammatory factors with an abnormal release of cytokines such as IL-1, IL-6, TNF-α, MCP-1, RANTES, among others." (PMID 39408993, 2024). "BALB/c mice treated with Dermatophagoides farinae extract/2,4-dinitrochlorobenzene were defined as a mouse model of atopic dermatitis, either with inflamed HaCaT cells and HUVECs exposed with TNF-α/IFN-γ stimulation were applied for a cell model of atopic dermatitis." (PMID 37264030, 2023). "The fact that it effectively reduces the increase in TNF-α and IL-6 induced by lipopolysaccharide (LPS) stimulation in RAW264.7 cells, along with the significant decrease in TNF-α and IL-6 observed in an atopic dermatitis animal model, consistently aligns with the findings of our study." (PMID 37686078, 2023).
atopic dermatitis (continued). "Our findings are in line with other preclinical studies beyond atopic dermatitis wherein HSP90 inhibition exerted anti-inflammatory effects by targeting several inflammatory cytokines (e.g. TNF, IL-1β, and IL-6) and signalling pathways (e.g. ERK1/2, p38, and JNKs)." (PMID 38274815, 2023). "The stimulation of human peripheral blood mononuclear cells (PBMCs) from healthy individuals with EVs from M. sympodialis resulted in increased levels of TNF-α, while in patients with atopic eczema this resulted in an increased production of both IL-4 and TNF-α." (PMID 37892168, 2023). "In this study, we aimed to evaluate the inhibitory effects of Donkey Hide Gelatin (DHG) water extract on DNCB-induced atopic dermatitis in NC/Nga mice and on tumor necrosis factor (TNF)-α/interferon (IFN)-γ-treated keratinocytes and to investigate its underlying molecular mechanisms." (PMID 35694270, 2022). "Therefore, TNF-α/IFN-γ-stimulated HaCaT keratinocytes have been commonly adopted as an in vitro model of inflammatory skin diseases such as atopic dermatitis." (PMID 36235070, 2022). "Interestingly, the immunoproteasome inhibitor PKS3053 prevented the induction of several IFN-regulated genes and the pro-inflammatory cytokines TNF and IL-1β to tape stripping in a mouse model for atopic dermatitis." (PMID 36591277, 2022). "For this reason, delanzomib may be available for the treatment of some systemic autoimmune diseases including RA, psoriasis vulgaris, atopic dermatitis, and so on, where TNF-α plays an important role in the pathophysiology." (PMID 34880764, 2021). "Astragalin is associated with various pharmacological and biological activities, including anti-inflammatory, antioxidant activity, anti-atopic dermatitis activity, TNF-a, IL-1b, and IL-6 production inhibiting activity, and inhibiting histamine release in human blood cells." (PMID 33968110, 2021). "Increased expression of these cytokines has been linked to the pathogenesis of many inflammatory skin disorders, e.g., TNF, IFN-γ, and IL-6 are highly expressed in psoriatic lesions, while IFN-γ and TNF are associated with the chronic phase of atopic dermatitis." (PMID 32983167, 2020). "They reported that treatment of atopic dermatitis mouse model with ZnO NPs suppresses local inflammation by down-regulation of the expression levels of pro-inflammatory cytokines such as IL-1β, IL-6, and TNF-α." (PMID 30127816, 2018). "It has consistently been shown that the mRNA levels of TNF-α and IL-6, which have been implicated in the pathogenesis of atopic dermatitis, are higher in atopic obese rats than in the nonobese ones." (PMID 28696379, 2017). "Its increased expression, as observed in atopic dermatitis, led to decreased expression of an important epidermal barrier component, filaggrin, and increased expression of pro-inflammatory cytokines, including TNFα and CCL5." (PMID 24260356, 2013). "Maternal inflammatory cytokines (MCP‐1, IL‐10, TNF‐α) in late pregnancy have been shown to correlate with offspring's levels of the same cytokines in cord blood and at age 1 year but not with the offspring's risk of atopic eczema." (PMID 40714954, 2025). "For example, increased levels of interleukin (IL)-6 andtumor necrosis factor (TNF)-α, which exacerbate immune systemhyperactivity and compromise skin barrier function, often result in chronicinflammation observed in conditions such as urticaria and atopic dermatitis." (PMID 41209500, 2025). "Notably, astersaponin J exhibited a dose-dependent reduction in IL-1β, IL-6, and TNF-α levels, suggesting that it could be a potential candidate of a therapeutic agent for atopic dermatitis." (PMID 39519643, 2024). "Furthermore, atopic dermatitis could be mitigated by TGFβ-dependent suppression of TNFα secretion from mast cells." (PMID 37626914, 2023).